HTT (huntingtin)
Diseases named in the same sentence as HTT in open-access papers (continued):
Sharing a sentence is not in itself a finding about the gene and the disease.
Huntington disease (continued). "Huntington’s disease is a rare autosomal dominant neurodegenerative disease of CNS caused by elongation of CAG codon in the huntingtin gene, which leads to the development of huntingtin protein (Htt)." (PMID 34959331, 2021). "Huntington’s disease (HD) is a ND caused by an expanded CAG trinucleotide repeat at the N-terminus of the HTT gene that results in amyloid formation." (PMID 34685723, 2021). "Huntington’s disease has also been ascribed to misfolding of huntingtin protein caused by an increase of polyglutamine." (PMID 33670336, 2021). "More recent research implicated a cellular deficit of Mn in the pathogenesis of Huntington’s disease (HD), a fatal neurodegenerative disease caused by expansion of a polyglutamine domain at the N-terminus of the huntingtin protein." (PMID 33671818, 2021). "Huntington’s disease (HD) is a neurodegenerative disorder caused by a CAG repeat expansion in exon 1 of huntingtin (HTT)." (PMID 33731741, 2021). "Huntington’s disease (HD) is an inherited autosomal dominant neurodegenerative disorder caused by accumulated mutant Huntingtin (Htt) protein with a poly-glutamine expansion (encoded by CAG trinucleotide repeat)." (PMID 34512273, 2021). "Huntington's disease (HD) is a progressive autosomal-dominant neurodegenerative disorder caused by the expansion of glutamine repeats in huntingtin protein (HTT)." (PMID 33609766, 2021). "The mutations in the parkin gene represent a very low risk of developing the Parkinson disease while the example of Huntington disease represented a high risk, as a mutation in the Huntingtin gene will always lead to the manifestation of the disease." (PMID 34241790, 2021). "Huntington's disease (HD) is a fatal neurodegenerative disorder caused by an expansion of the CAG repeats in the huntingtin gene (HTT)." (PMID 34608934, 2021). "Huntington's disease (HD) is an autosomal-dominant inherited neurodegenerative disorder that is caused by expansion of a CAG-repeat tract in the huntingtin gene and characterized by motor impairment, cognitive decline, and neuropsychiatric disturbances." (PMID 34621236, 2021). "Huntington’s disease (HD) is one of neurodegenerative diseases, and is defined as a monogenetic disease due to the mutation of Huntingtin gene." (PMID 34412645, 2021). "Lastly, we extended the protein analysis to the HTT (Huntingtin) gene causing Huntington’s disease (HD), as an example of a neurodegenerative disorder for which modeling pathological processes in patient-specific cells is not without challenges." (PMID 34744760, 2021). "Huntington’s disease (HD) is a rare neurodegenerative disorder caused by an expansion of CAG trinucleotide repeat located in the exon 1 of Huntingtin (HTT) gene in human chromosome 4." (PMID 34830381, 2021). "Huntington's disease (HD) is an autosomal dominant neurodegenerative disorder caused by an expanded trinucleotide CAG repeat in the HTT gene." (PMID 33493786, 2021). "Huntington’s disease (HD) is a hereditary neurodegenerative disorder caused by expansion of cytosine-adenine-guanine (CAG) trinucleotide repeats in the huntingtin (HTT) gene." (PMID 34911927, 2021). "Huntington’s disease (HD) is a hereditary neurodegenerative disorder caused by the expression of mutant huntingtin (mHtt)." (PMID 35153755, 2021). "Autosomal-dominant glutamine-encoding CAG repeat expansions in the Huntingtin gene (HTT) cause Huntington's disease (HD) while CAG repeats in the coding regions of various unrelated ataxin genes lead to spinocerebellar ataxias (SCA)." (PMID 33729487, 2021). "Huntington’s disease (HD) is an autosomal dominant neurodegenerative disease caused by an expansion of the polyglutamine tract in the N-terminal of the huntingtin (Htt) protein." (PMID 34631219, 2021).
Huntington disease (continued). "Huntingtin protein (Htt) is ubiquitously expressed throughout the body and was identified as the product of the gene mutated in Huntington’s disease (HD), a devastating, autosomal dominant, neurodegenerative disorder with no cure yet available." (PMID 34215255, 2021). "Huntington’s disease (HD) is caused by a CAG repeat expansion in the gene that encodes for the huntingtin (HTT) protein, resulting in an expanded polyglutamine repeat." (PMID 34108866, 2021). "Huntington’ disease (HD) is caused by the expansion of CAG repeats in exon 1 of the Huntingtin (HTT) gene." (PMID 34880223, 2021). "Huntington’s disease (HD) is caused by an expansion of the CAG repeat in the huntingtin gene leading to preferential neurodegeneration of the striatum." (PMID 33786806, 2021). "Huntington’s disease (HD) is a fatal autosomal neurodegenerative disease caused by a poly-CAG expansion in the first exon of the HTT gene." (PMID 34732320, 2021). "Huntington’s disease (HD) is an autosomal dominant, incurable neurodegenerative disease caused by mutation in the huntingtin gene (HTT)." (PMID 34073127, 2021). "Huntington’s disease (HD) is a chronic neurodegenerative disorder caused by an expansion of polyglutamine repeats in exon 1 of the Huntingtin gene." (PMID 34721539, 2021). "Huntington’s disease (HD) is caused by a mutation in the HTT gene coding for the huntingtin protein." (PMID 34299328, 2021). "Huntington’s disease (HD) is an inherited neurodegenerative disorder caused by a CAG repeat expansion in the huntingtin gene (HTT)." (PMID 34658796, 2021). "Huntington’s disease (HD) is an autosomal dominant neurodegenerative disorder caused by a CAG trinucleotide repeat expansion in the huntingtin (HTT) gene, which encodes an expanded polyglutamine tract in the huntingtin (HTT) protein." (PMID 34648564, 2021). "Huntington disease (HD) is a fatal neurodegenerative disorder caused by an expanded CAG repeat in the huntingtin (HTT) gene." (PMID 34448021, 2021). "Recently, Abhd11os (ABHD11-AS1 in human) has been identified as a striatal-specific lncRNA and proposed to play a neuroprotective role against mutant Huntingtin (HTT), a protein implicated in Huntington’s Disease." (PMID 34349622, 2021). "Huntington’s disease (HD) is caused by a CAG trinucleotide repeat expansion in the first exon of the huntingtin (HTT) gene coding for the huntingtin (HTT) protein." (PMID 34504195, 2021). "Huntington disease (HD) is a neurodegenerative trinucleotide repeat disorder caused by an expanded poly-glutamine (polyQ) tract in the mutant huntingtin (mHTT) protein." (PMID 34239038, 2021). "Huntington’s disease (HD) is a rare autosomal dominant disorder caused by an expansion of cytosine-adenine-guanine (CAG) repeats within the huntingtin (Htt) gene." (PMID 34440645, 2021). "Huntington’s Disease (HD) is a polyglutamine (PolyQ)-related disorder caused by an expanded CAG repeat (>36) in the first exon of the HTT gene." (PMID 34349622, 2021). "Huntington’s disease (HD) is caused by a CAG repeat expansion in exon 1 of the huntingtin (HTT) gene that leads to the insertion of a polyglutamine (PolyQ) tract in HTT protein." (PMID 33996898, 2021). "Huntington’s disease (HD) is caused by expansion of polyglutamine repeats in the protein huntingtin, which affects the corpus striatum of the brain." (PMID 34573100, 2021). "Huntington's disease (HD) is a heritable degenerative brain disease caused by a mutation in the huntingtin gene with excessive repeats of the base triplet cytosine–adenine–guanine (CAG), which codes for the aminoacid glutamine." (PMID 33070471, 2021). "Huntington’s disease (HD) results from an expansion mutation in the polyglutamine tract in huntingtin." (PMID 34648564, 2021). "Huntingtin (Htt) protein is the product of the gene mutated in Huntington’s disease (HD), a fatal, autosomal dominant, neurodegenerative disorder." (PMID 34215255, 2021).
Huntington disease (continued). "Huntington's disease (HD) is a fatal autosomal‐dominant neurodegenerative disease caused by a trinucleotide CAG repeat expansion of the huntingtin gene (HTT) that affects 1 in every 10 000 individuals in the United States." (PMID 33710799, 2021). "Huntington’s disease (HD) is a neurodegenerative disease, caused by the aggregation of the huntingtin (HTT) protein in the human brain nerve cells." (PMID 34869596, 2021). "Huntington’s disease (HD) is caused by a CAG-repeat expansion mutation in the Huntingtin (HTT) gene." (PMID 34357961, 2021). "Huntington’s disease (HD) is a neurodegenerative disorder caused by an abnormal CAG trinucleotide repeat expansion within exon 1 of the huntingtin (HTT) gene." (PMID 34681268, 2021). "In the context of Huntington’s disease (HD), mutant huntingtin (Htt) has been associated with the opening of mPTP in the inner mitochondrial membrane, triggering the release of cytochrome c and activating apoptosis." (PMID 33791300, 2021). "Despite the strong evidence linking the aggregation of the Huntingtin protein (Htt) to the pathogenesis of Huntington’s disease (HD), the mechanisms underlying Htt aggregation and neurodegeneration remain poorly understood." (PMID 34772920, 2021). "The polyglutamine expansion in the huntingtin (HTT) protein causes the neurodegenerative disorder Huntington’s disease (HD)." (PMID 34575100, 2021). "Huntington’s disease (HD) is caused by a polymorphic trinucleotide CAG repeat expansion in the HTT gene that encodes the polyglutamine (polyQ) repeat in the N-terminal region of Huntingtin (Htt)." (PMID 34245328, 2021). "Huntington’s disease (HD) is an autosomal inherited neurodegenerative disorder caused by an expanded CAG codon repeat in the huntingtin gene." (PMID 35153755, 2021). "Dynein also binds to Huntingtin (HTT), the causative protein for Huntington’s disease (HD), while DCTN1 binds to HTT-associated protein 1 (HAP1)." (PMID 33924373, 2021). "Huntington’s disease (HD) is caused by the expansion of a CAG trinucleotide repeat in the coding region of the huntingtin (Htt) gene." (PMID 34776869, 2021). "We then evaluated the capability of AAV2.retro to deliver disease-related gene cargo to biologically-relevant NHP brain circuits by packaging a fragment of human mutant HTT, the causative gene mutation in Huntington’s disease." (PMID 32332773, 2020). "Huntington’s disease (HD) is a neurodegenerative disorder with a progressive loss of medium spiny neurons in the striatum and aggregation of mutant huntingtin in the striatal and cortical neurons." (PMID 33154393, 2020). "Huntington’s disease is a fatal autosomal dominant disorder caused by misfolding and aggregation of the huntingtin (HTT) protein due to expansion of a polyglutamine tract (CAG repeats) within its N-terminal domain." (PMID 33168089, 2020). "Huntington’s Disease (HD) is an inherited condition caused by an abnormal expansion of CAG trinucleotide repeats in the mutant huntingtin (mHTT) gene." (PMID 32302302, 2020). "The length of the polyglutamine (polyQ) repeat region in the huntingtin protein correlates with a propensity for the protein to aggregate and is associated with Huntington’s disease." (PMID 33348896, 2020). "Intriguingly, BDNF is transported within neurons by the Huntingtin protein (HTT), so named because mutations in HTT underlie Huntington's disease." (PMID 31913581, 2020). "Huntington’s disease (HD) is a dominantly inherited pathology caused by the accumulation of mutant huntingtin protein (HTT) that contains an expanded N-terminal polyglutamine (polyQ) tract." (PMID 33633561, 2020). "10-NCP, as an autophagy enhancer, regulates the degradation of mutant huntingtin (mHtt) in neurons, the protein that causes Huntington’s disease." (PMID 32043463, 2020). "Huntington’s disease (HD) is caused by the expansion of cytosine-adenine-guanine (CAG) repeats in the huntingtin gene, and the CAG repeat length is associated with an earlier disease onset." (PMID 32784364, 2020).
Huntington disease (continued). "Huntington’s disease (HD) is an autosomal dominant neurodegenerative disease caused by CAG repetition in the gene encoding huntingtin protein (HTT) and is characterized by progressive motor, cognitive and psychiatric symptoms." (PMID 32144144, 2020). "Mutations that cause Huntington’s Disease involve a polyglutamine (polyQ) sequence expansion beyond 35 repeats in exon 1 of Huntingtin." (PMID 32735619, 2020). "In fact, mutations in huntingtin cause the accumulation of LDs and influences the development of Huntington’s disease (see Section 5.1)." (PMID 33143278, 2020). "Huntington’s disease (HD) is an autosomal-dominant neurodegenerative disorder caused by a CAG expansion in the exon-1 of the Huntingtin gene." (PMID 32732871, 2020). "Huntington disease (HD) occurs due to the mutated huntingtin gene and affects the medium spiny neurons in the striatum as well as neurons in the cortex, leading to symptoms such as chorea (jerky movements), rigidity and progressive motor failure." (PMID 32210766, 2020). "Huntington’s disease is a rare neurodegenerative disease caused by a cytosine–adenine–guanine (CAG) trinucleotide expansion in the Huntingtin (HTT) gene." (PMID 33049985, 2020). "Huntington's disease (HD) is an autosomal dominant neurodegenerative disorder caused by a CAG trinucleotide expansion in exon 1 of the Huntingtin (HTT) gene, which presents with a combination of motor, cognitive, and psychiatric deficits." (PMID 31724242, 2020). "Huntington’s disease (HD) is caused by a CAG trinucleotide repeat expansion in the huntingtin gene (HTT), which encodes an expanded polyglutamine stretch in the huntingtin protein (HTT)." (PMID 32984817, 2020). "Another example is Huntington ​disease, which is caused by a genetic alteration in the huntingtin (HTT) gene, leading to the production of a mutated protein that is toxic to certain cell types." (PMID 32190832, 2020). "Huntington’s disease (HD) is caused by a mutation in the huntingtin (HTT) gene encoding mutant huntingtin protein (mHTT) with an expanded polyglutamine tract (PolyQ)." (PMID 33276680, 2020). "Huntington’s disease (HD) is an autosomal dominant neurodegenerative disorder caused by a cytosine-adenine-guanine (CAG) trinucleotide repeat expansion in the huntingtin gene." (PMID 33114553, 2020). "Huntington’s disease (HD) is an actively investigated neurodegenerative disorder caused by an expansion of CAG triplets (>36) in the first exon of the HTT gene encoding the huntingtin protein." (PMID 33182269, 2020). "Huntington’s disease is an autosomal dominant disorder associated with a mutation in the gene encoding huntingtin (Htt)." (PMID 32107381, 2020). "Huntington’s disease (HD) is caused by Huntingtin (Htt) gene mutation resulting in the loss of striatal GABAergic neurons and motor functional deficits." (PMID 32107381, 2020). "A recent study using several Huntington’s disease models showed a role for Gal3 in the regulation of the inflammatory response towards membrane damage caused by the huntingtin mutant." (PMID 32906744, 2020). "Huntington’s disease (HD) is a neurodegenerative pathology, caused by defects of the IT-15 gene encoding Huntingtin protein, a large 348 kDa protein predicted to form an elongated and flexible superhelix." (PMID 33167595, 2020). "It is of note that huntingtin (Htt) protein, associated with the neurodegenerative disease Huntington’s disease, was observed to interact “in vitro” with the HAT domains of PCAF, CBP and p300 and to inhibit their HAT activity." (PMID 32238831, 2020). "Huntington’s disease is caused by an expansion of CAG repeats in exon 1 of the human huntingtin gene (HTT) located on chromosome 4." (PMID 33505246, 2020). "Huntington's disease is an autosomal dominant neurodegenerative condition caused by a CAG expansion in the HTT gene, resulting in the expression of mutant huntingtin protein, which is thought to be the predominant toxic agent." (PMID 32470422, 2020).
Huntington disease (continued). "HTTQ103 consists of a stretch of 103 polyglutamine residues deriving from the abnormal CAG expansion found in Huntington disease–causing huntingtin mutant." (PMID 32163402, 2020). "Huntington’s disease is an autosomal-dominant neurodegenerative disease caused by a CAG trinucleotide repeat expansion that gives place to a polyglutamine region in the huntingtin protein (HTT)." (PMID 32116490, 2020). "Huntington's disease (HD) is a fatal neurodegenerative disease caused by the increase of the polyglutamine bundle in Huntington's protein (HTT), resulting in its accumulation in nuclear and cytoplasmic inclusions." (PMID 32148781, 2020). "BLMH has been implicated in Huntington’s disease, through cleavage of huntingtin, and in Alzheimer’s disease through the processing of amyloid precursor protein." (PMID 32821252, 2020). "For example, Huntington’s disease (HD) is an intractable autosomal dominant disorder caused by aggregation-prone mutant huntingtin (mHtt), which has an extended N-terminal polyQ tract." (PMID 32326273, 2020). "Huntington’s disease (HD) is a fatal neurodegenerative disorder caused by the expansion of CAG repeats in exon 1 of the huntingtin gene (HTT)." (PMID 32182692, 2020). "A mutation in exon 1 of the HTT gene, which results in the pathogenic expansion of a polyglutamine tract near the N-terminus of the protein, causes Huntington’s disease (HD), a lethal neurodegenerative disease with autosomal dominant inheritance." (PMID 33297953, 2020). "A type of hereditary ND, Huntington’s disease (HD) is an autosomal dominant disorder caused by CAG repeat expansion within the Huntington (HTT) gene." (PMID 32351395, 2020). "For instance, in R6/1 mouse models of Huntington’s disease (HD), mutated huntingtin is overexpressed in CCs; this causes decreased quantal secretion, smaller quantal size and faster kinetics of the exocytotic fusion pore, pore expansion, and closure." (PMID 32178443, 2020). "Huntington’s disease (HD) is caused by an expansion of CAG triplets in the huntingtin gene, leading to severe neuropathological changes that result in a devasting and lethal phenotype." (PMID 33505246, 2020). "Similar to SCA3, Huntington's disease (HD), an autosomal dominant neurodegenerative disease, is also caused by polyQ expansion in the HTT protein." (PMID 33425926, 2020). "Huntington Disease (HD) is an inherited movement disorder caused by expanded CAG repeats in the Huntingtin gene." (PMID 32070434, 2020). "Huntington’s disease (HD) is a rare autosomal dominant neurodegenerative disease caused by a mutation within the Huntingtin gene leading to the expansion of a CAG triplet repeat encoding for a polyglutamine (polyQ) tract." (PMID 33003610, 2020). "Huntington's disease is a progressive neurodegenerative disorder with autosomal-dominant heritability that is caused by CAG trinucleotide repeat expansion in the huntingtin gene (HTT)." (PMID 33425919, 2020). "Huntington’s disease is caused by a CAG repeat expansion mutation in exon 1 of the huntingtin gene (HTT)." (PMID 33233776, 2020). "Huntington’s disease (HD) is a fatal neurodegenerative disease caused by the expansion of cytosine-adenine-guanine (CAG) repeats in the huntingtin gene." (PMID 32784364, 2020). "Huntington disease (HD) is a fatal neurodegenerative disease caused by a pathogenic expansion of a CAG repeat in the huntingtin (HTT) gene." (PMID 31745548, 2020). "Huntington’s disease (HD) is a neurological disorder caused by an expansion in the cytosine-adenine-guanine (CAG) trinucleotide repeat region in the huntingtin (HTT) gene." (PMID 31988371, 2020). "Polyglutamine expansions in the protein huntingtin (HTT) form cytoplasmic inclusion bodies (huntingtin bodies) and are causative for hereditary forms of Huntington’s disease." (PMID 33276458, 2020). "Neurodegenerative Huntington's disease (HD) is caused by CAG trinucleotide expansion in the huntingtin gene (HTT; Walker, 2007)." (PMID 32530575, 2020).